HNF1B (HNF1 homeobox B)
Diseases named in the same sentence as HNF1B in open-access papers (continued):
Sharing a sentence is not in itself a finding about the gene and the disease.
prostate carcinoma (continued). "Likewise, HNF1B was shown to be part of five gene expression signature predictive of relapse in prostate cancer patients." (PMID 33580750, 2021). "The observed interaction between HNF1B with CDKN2A contributes to suppression of SMAD6 and TGF‐β signalling, which suggests that HNF1B may play important roles in prostate cancer initiation and progression." (PMID 33174391, 2020). "To further elucidate the mechanism how HNF1B influences the cell cycle, we re‐explored and analysed the RNA‐seq data, and focused on Cyclin D1, which a key regulator of cell cycle (G1‐ phase) for both normal and tumour cells, is negatively regulated by HNF1B in prostate cancer cells." (PMID 33174391, 2020). "However, the molecular mechanisms involved in how HNF1B influences the proliferation of prostate cancer cells are still not well understood." (PMID 33174391, 2020). "Except for methylation, another classic mechanism of protein inactivation is a truncating gene mutation, but that does not seem to play a role in prostate carcinoma, as HNF1B mutations are a rare event in this type of tumor." (PMID 32873863, 2020). "Methylation of the HNF1B promoter was found in 231/491 (47%) prostate carcinoma samples." (PMID 32873863, 2020). "However, the levels of protein expression of HNF1B in prostate cancer are not well known, and the mechanisms playing role in its regulation are of interest." (PMID 32873863, 2020). "We thus hypothesized that HNF1B inhibits prostate cancer tumorigenesis by suppression the EMT capability through repressing SLUG." (PMID 31636385, 2020). "We found that HNF1B could be epigenetically repressed by EZH2 in prostate cancer cell lines, and its expression is reversely correlated with EZH2 expression in several cohorts of prostate cancer samples, including TCGA database and in-house collection." (PMID 31636385, 2020). "In addition, we alleviated HNF1B‐mediated cell growth inhibition of prostate cancer cells by overexpression of Cyclin D1 both in vitro and in vivo." (PMID 33174391, 2020). "Re‐introduction of SMAD6 restored Cyclin D1 expression and cell proliferation, which supports the hypothesis that HNF1B inhibits prostate cancer cell proliferation by direct repression of SMAD6." (PMID 33174391, 2020). "Our results support the oncosuppressive role of HNF1B in prostate carcinoma, which may be silenced due to promoter methylation and other mechanisms, but not due to gene mutation, which seems to be very rare in PC." (PMID 32873863, 2020). "Importantly, we find that higher HNF1B expression strongly predicts better prognosis of prostate cancer, alone or together with lower EZH2 expression." (PMID 31636385, 2020). "Here in this study, we find that the tumor suppressor HNF1B is repressed by EZH2 in prostate cancer cell lines, and functions together with RBBP7 in suppressing EMT through down-regulation of SLUG expression, which expands our knowledge of how EZH2 is involved in this deleterious disease." (PMID 31636385, 2020). "Here, we demonstrated that HNF1B inhibited the proliferation rate of prostate cancer cells." (PMID 33174391, 2020). "Importantly, our study clearly demonstrates a tumor suppressive function of RBBP7 in prostate cancers when HNF1B is present." (PMID 31636385, 2020). "In our study, we have found HNF1B mutations (VUS – variant of uncertain significance) in 1/77 cases (1.3%) only, which is in accordance with the TCGA study showing only one likely pathogenic mutation in a dataset containing 491 cases of prostate cancer (0.2%)." (PMID 32873863, 2020). "HNF1β is upregulated in human prostate cancer and favors cell proliferation and tumor progression." (PMID 28219405, 2017). "In conclusion, while the two examined HNF1B variants conclusively have pleiotropic effects on both T2D and prostate cancer, the pleiotropy apparently does not extend to other cancer types." (PMID 20526366, 2010).
prostate carcinoma (continued). "We report here that disruption of the amount or nature of transcripts expressed from the LMTK2, MSMB and HNF1B genes, identified in the genome wide scans for prostate cancer, may be important in the aetiology of this disorder." (PMID 20569440, 2010). "HNF1B was previously known to be mutated in individuals with maturity-onset diabetes of the young type 5 (MODY 5), but a biological explanation of the impact of the identified common variation on T2D and prostate cancer risk remains elusive." (PMID 20526366, 2010). "The examined HNF1B variants have a highly specific effect on prostate cancer risk with no apparent association with any of the other studied cancer types." (PMID 20526366, 2010). "Thus, our results provide for the first line evidence of EZH2-mediated repression of HNF1B during prostate cancer progression, which may also exist in other cancer types." (PMID 31636385, 2020). "Thus, Cyclin D1 is a functional target of HNF1B in prostate cancer cells." (PMID 33174391, 2020). "However, it would be worthwhile to investigate the associations of the HNF1B variants for T2D, prostate cancer, and other cancers, also in non-Caucasian populations." (PMID 20526366, 2010). "In previous study, we have identified HNF1B as a transcriptional target of EZH2 that can rescue EZH2‐mediated migration and cell growth in prostate cancer." (PMID 33174391, 2020). "EZH2 binds HNF1B locus and suppresses HNF1B expression in prostate cancer cell lines, which is further supported by the reverse correlation between EZH2 and HNF1B expression in clinical samples." (PMID 31636385, 2020). "To further validate the pathological relevance of such connection, we set out to determine the HNF1B expression pattern, and its relationship with EZH2 level in prostate cancer samples." (PMID 31636385, 2020). "Our findings elucidate a previously underappreciated path of EZH2 exerting its oncogenic effects through repressing HNF1B and promoting SLUG mediated EMT process in prostate cancer." (PMID 31636385, 2020). "In a recent study the authors found that EZH2 binds to the HNF1B locus and suppresses the HNF1B gene expression in prostate cancer cell lines, with a reverse correlation between EZH2 and HNF1B expression." (PMID 32873863, 2020). "Next, we examined HNF1B and EZH2 expression in prostate cancer cell lines with different metastatic potentials." (PMID 31636385, 2020). "Consistently, restored HNF1B expression significantly suppresses EZH2-mediated overgrowth and EMT processes, including migration and invasion of prostate cancer cell lines." (PMID 31636385, 2020). "These genes include TP63 for bladder cancer, FGFR2 and MAP3K1 for breast cancer, HNF1B for ovarian cancer, KLK3 for prostate cancer, and CDKN2A for skin cancer." (PMID 26374197, 2015). "We also report a potential role for alternative mRNA processing of the HNF1B and MSMB genes in the aetiology of prostate cancer." (PMID 20569440, 2010). "We found highly significant disturbances to the profile of isoforms expressed in prostate cancer in the case of the MSMB and HNF1B genes." (PMID 20569440, 2010). "Our results indicate that the amount or nature of mRNA transcripts expressed from the LMTK2, HNF1B and MSMB candidate genes is altered in prostate cancer, and provides further evidence for a role for these genes in this disorder." (PMID 20569440, 2010). "However, RBBP7 can also bind to HNF1B as part of multiple transcriptional repressor complexes, thereby inhibiting EMT in prostate cancer via direct suppression of EMT factor SLUG expression, except that HNF1B is often repressed by EZH2 overexpression." (PMID 38028543, 2023). "Decreased expression of the overall HNF1B mRNA in the large intestine and prostate cancer samples compared with the corresponding non-tumour samples was observed (p = 0.019 and p = 0.047, respectively)." (PMID 34997048, 2022).
prostate carcinoma (continued). "However, in prostate cancer, upregulation of EZH2 suppresses the levels of the RBBP7/HNF1B transcriptional complex via direct inhibition of HNF1B expression, promoting SLUG transcription." (PMID 34736517, 2021). "Beyond prostate cancer cell lines, we also observed a significant reverse correlation between EZH2 and HNF1B expression in patient samples, and the high EZH2 and low HNF1B pattern is strongly associated with poor prognoses and advanced metastatic state (our own collection and public database)." (PMID 31636385, 2020). "Mechanistically, HNF1B interacts with RBBP7, a component of multiple transcription repressor complexes, and represses SLUG expression and EMT process to suppress the cancer phenotypes of prostate cancer cells." (PMID 31636385, 2020). "In a mouse model, the authors compare HNF1B and ECI2 protein expression at different stages of prostate cancer development and concluded that during tumor progression, the protective effect of HNF1B is lost, and that is associated with an increased expression of ECI231." (PMID 32873863, 2020). "In conclusion, the results of our study showed that the expression of HNF1B on an IHC level is very low in prostate carcinoma, does not differ between PC and AH, and did not correlate with any clinical outcomes." (PMID 32873863, 2020). "Taken together, our findings established a previously unknown connection between HNF1B and EZH2 in prostate cancer samples and cell lines." (PMID 31636385, 2020). "However, the specific interaction between HNF1B and ECI2 is uncertain, but according to recent data, the increased gene expression of ECI2 may promote prostate cancer growth." (PMID 32873863, 2020). "However, the precise roles and mechanisms of HNF1B in prostate cancer proliferation are still not clear." (PMID 33174391, 2020). "Consistently, ectopically expression of HNF1B in prostate cancer cell lines, PC-3 and DU145, but not normal prostate cell line PNT2a, led to significantly reduced proliferation and paxillin associated adhesion reflecting a reduced Epithelial–mesenchymal transition (EMT) ability." (PMID 31636385, 2020). "To determine whether epigenetic inactivation could play a role in regulating HNF1B expression levels in prostate cancer, we compared methylation levels at the HNF1B promoter between cancer and matched non-cancer samples in two cohorts." (PMID 27732966, 2016).
maturity-onset diabetes of the young type 5 (46 papers, 2009 to 2026). "Maturity-Onset Diabetes of the Young Type 5 (MODY5), also referred to as Renal Cysts and Diabetes (RCAD) syndrome, is specifically attributed to heterozygous variants or deletions within the hepatocyte nuclear factor 1-beta (HNF1B) gene, also known as TCF2." (PMID 41009948, 2025). "HNF1B haploinsufficiency leads to a diverse and highly variable clinical phenotype spectrum, potentially leading to renal cysts and diabetes syndrome (RCAD) and, when associated with neuropsychiatric abnormalities, 17q12 deletion syndrome." (PMID 39976628, 2025). "Loss of function or a truncated HNF1b allele can result in maturity onset diabetes of the young, type 5 (MODY5), which is an autosomal dominant disorder, characterized by early onset usually 17–25.8 years old and is often accompanied by genital malformation." (PMID 32623698, 2021). "Four cases had 17q12 deletion, their genomic regions involved hepatocyte nuclear factor 1 homeobox B (HNF1B), associated with renal cyst and diabetes (RCAD) syndrome." (PMID 32211073, 2020). "Renal Cysts and Diabetes (RCAD) syndrome is caused by heterozygous mutations in the HNF1B gene, encoding the transcriptional factor hepatocyte nuclear factor-1B." (PMID 30778115, 2019). "For the identification of significant urinary peptides related to the RCAD syndrome, we compared the urinary proteome profiles of 22 patients carrying HNF1B heterozygous mutations with 22 age- and gender-matched healthy controls." (PMID 30778115, 2019). "Known causative gene and transcription factor HNF1B resides within this region and heterozygous mutations result in maturity onset diabetes of the young type 5 (MODY5)." (PMID 29434669, 2018). "Initially, mutations in the HNF1B gene were described in association with maturity onset diabetes of the young (MODY type 5)." (PMID 29497606, 2018). "This variant affects transcription factor HNF1B, which is involved in the organogenesis of the kidney, genitourinary tract, liver, lungs, intestine and pancreas; hence it is also known as renal cyst and diabetes (RCAD) syndrome." (PMID 40901483, 2025). "Interestingly, another case report has described end-stage renal failure secondary to probable DKD in a patient with HNF1β mutation and RCAD syndrome." (PMID 29764441, 2018). "Renal cysts and diabetes syndrome (RCAD) is caused by anomalies of the gene for hepatocyte nuclear factor 1 beta (HNF1B) and is also called maturity-onset diabetes of the young type 5 (MODY5)." (PMID 40839116, 2026). "Maturity-Onset Diabetes of the Young Type 5 (MODY5) is caused by heterozygous pathogenic variants in the HNF1B gene, encoding the transcription factor hepatocyte nuclear factor-1β." (PMID 41009948, 2025). "Maturity-onset diabetes of the young type 5 (MODY5) is a rare autosomal-dominant monogenic diabetes caused by functional loss of the transcription factor, hepatocyte nuclear factor-1 beta (HNF1B)." (PMID 42158912, 2026). "The deletion of 17q12 includes several genes, and among these, the HNF1β gene [related to maturity-onset diabetes of the young type 5 (MODY5)] is the best characterized." (PMID 40256398, 2025). "Another important example where CMA can be useful is when HNF1B-related kidney disease (also known as renal cysts and diabetes syndrome (RCAD)) is suspected." (PMID 39945861, 2025). "Included within the genetic forms of CAKUT/cystic dysplasia is kidney disease associated with pathogenic variants in hepatocyte nuclear factor 1 beta (HNF1B), the causative gene for maturity-onset diabetes of the young, type 5 (MODY5)." (PMID 38676761, 2024). "Loss-of-function deletions in HNF1B triggering maturity-onset diabetes of the young, type 5 [MODY5; also known as renal cyst and diabetes syndrome (RCAD); OMIM 137920; Box 1] have also been reported to cause Müllerian phenotypes in two patients." (PMID 34160006, 2021).
maturity-onset diabetes of the young type 5 (continued). "Mutations of HNF-1β in humans produce maturity-onset diabetes of the young type 5 (MODY5) and cystic abnormalities of the kidney (renal cyst and diabetes-syndrome, RCAD-syndrome)." (PMID 33168884, 2020). "In contrast, HNF1B mutations (MODY5) cause Renal Cysts and Diabetes (RCAD) syndrome." (PMID 41614934, 2026). "Importantly, maturity-onset diabetes in the young type 5 (MODY5), which is associated with HNF1B mutations, typically appears in adolescence and early adulthood; thus, this manifestation is usually absent when considering molecular testing in young children." (PMID 38196016, 2024). "As observed in MODY5 patients who are usually affected by renal cysts and diabetes (RCAD) syndrome, young mice with conditional knockout of HNF1B show polycystic kidneys, whereas knockout of HNF1B at P10 or later, results in significantly delayed cyst formation." (PMID 36361703, 2022). "HNF1B mutations can mimic ADPKD with important consequences for prognosis, the likelihood of comorbidities (for example, congenital hepatic fibrosis in PKHD1 or maturity onset diabetes of the young type 5 (MODY5) in HNF1B) and the risk of disease in siblings." (PMID 31118499, 2019). "Although not seen in our patient, HNF1B mutations can also cause maturity onset diabetes of the young type 5 (MODY5)." (PMID 29576871, 2018). "HNF1B-MODY has often been referred to as Renal Cysts and Diabetes (RCAD) syndrome, with a prevalence of cysts in 75% of patients in a previous study." (PMID 36793123, 2023). "Heterozygous variants in HNF1B or 17q12 microdeletions encompassing the HNF1B gene are associated with large intra-familial variation in TKD (with and without cysts), maturity-onset diabetes of the young type 5 (MODY5), CAKUT, and other organ involvement, including neuropsychiatric symptoms." (PMID 37628633, 2023).